NRP2 (neuropilin 2)
Diseases named in the same sentence as NRP2 in open-access papers (continued):
Sharing a sentence is not in itself a finding about the gene and the disease.
colorectal cancer (continued). "Notably, neuropilin-1 (NRP-1) and neuropilin-2 (NRP-2) have been identified as significant regulators of the tumor microenvironment in colorectal cancer (CRC)." (PMID 40430075, 2025). "In addition, the expression levels of neuropilin 1 and neuropilin 2, receptors for Sema3A, and Neogenin and deleted in colorectal cancer (DCC), receptors for Netrin-1, were evaluated by RT-qPCR." (PMID 36986209, 2023). "The studies were heterogeneous, but the data assessed indicates NRP-2 might have an impact on the metastatic potential of colorectal cancer cells." (PMID 35052853, 2022). "Also reduction of NRP2 expression by shRNA in colorectal cancer cells induces smaller tumors, decreased number of metastases and enhanced apoptosis in comparison with control shRNA in a murine xenograft model." (PMID 24212788, 2011). "NRP2 exerts a co-stimulatory effect of the TGF-β1 pathway in colorectal cancer cells." (PMID 21747928, 2011). "Indeed, we noticed that NRP2 expression enhances TGFβ1 signaling leading to constitutive Smad2/3 phosphorylation in colorectal cancer cells." (PMID 24212788, 2011). "The key objective is to provide an up-to-date literature review on the role of NRP-2 correlated to EMT, particularly in the progression of colorectal cancer." (PMID 35052853, 2022). "Research on the involvement of NRP-2 and EMT in colorectal cancer development is being systematically reviewed in the current paper." (PMID 35052853, 2022). "Patients with colorectal cancer (CRC) who express both NRP1 and NRP-2 have a worse prognosis than those who express either one neuropilin or none at all." (PMID 35052853, 2022). "There is a link between the development of colorectal cancer and an increase in the expression of the NRP genes NRP-1 and NRP-2, as well as NRP-1 in the vascular cells." (PMID 35052853, 2022). "NRP2 was suggested to play a direct role in EMT and a cross-talk between NRP2 and TGF-β1 signaling promotes colorectal cancer progression." (PMID 26573807, 2015). "Moreover, in colorectal cancer, miR-331-3p was shown to inhibit cell invasion and migration by directly targeting the 3′ untranslated region (3′-UTR) of the NRP-2 mRNA." (PMID 40430075, 2025). "According to a recent study, NRP-2 promotes cell migration in the presence of conditioned media from other types of cancer cells, but not from colorectal cancer cells." (PMID 35052853, 2022). "Neuropilin-2 (NRP2), another important regulator of lymphangiogenesis, was directly suppressed by miR-486-5p in colorectal carcinoma cells, leading to the reduction of peritumoral lymphatic microvessels in vivo, and thus demonstrating the suppressor role of miR-486-5p in colorectal carcinoma." (PMID 31616631, 2019). "Moreover, specific siRNA targeting NRP2 or treatment with pharmacological inhibitors of TGFβ-1 type 1 receptor (TGFβRI) prevented Smad2/3 phosphorylation and the NRP2-mediated EMT of colorectal cancer cells." (PMID 21747928, 2011). "NRP2 enhances VEGFR1 phosphorylation and subsequently activates multiple intracellular pathways like extracellular signal-regulated kinase (ERK) or phosphatidylinositol 3-kinase (PI3K) pathways in colorectal cancer cells and pancreatic adenocarcinoma cells." (PMID 24212788, 2011).
glioblastoma (14 papers, 2009 to 2025). The most malignant astrocytic tumor (WHO grade IV). "Based on this study, the SEMA3F-mimetic bsAb P1943-Nb2cL shows promise for preclinical mouse models and eventually clinical trials targeting glioblastoma and other cancers that express high levels of NRP2 and PLXNA1." (PMID 41391772, 2025). "As we already showed in glioblastomas, NRP-2 seems to be of minor importance in meningiomas as well." (PMID 33528717, 2021). "In glioblastoma cells, miR-331-3p suppresses neuropilin-2 (NRP-2) expression directly, and NRP-2 has been reported to predict treatment response of bladder cancer." (PMID 29599914, 2018). "To determine the effect of SEMA3F on intracellular signaling responses, we initially profiled levels of phosphokinases in the NRP2-expressing human glioblastoma cell line U87MG." (PMID 26156437, 2015). "miR-331-3p was reported to be downregulated in glioblastoma cell lines compared to normal brain, and overexpression of miR-331-3p inhibited proliferation, clonogenic growth, and migration in vitro by reducing mRNA levels of neuropilin-2." (PMID 29136645, 2017). "For example, SEMA3A promotes clonogenic growth of glioblastoma by the activation of NRP1 pathway and contributes to ischemia-induced brain damage through binding to NRP2/VEGFR1 receptor complex." (PMID 41391772, 2025). "Hence, we screened a panel of cells lines representing renal cancer (CAKI‐1, CAKI‐2, ACHN), bladder cancer (UC13, T24), and glioblastoma (U87MG), for expression of SEMA3C, EGFR, MET, Plexin B1, Plexin D1, NRP1, and NRP2." (PMID 29348142, 2018). "Focusing on the brain studies, there is one gene target of miR-331 which is the neuropilin 2 (NRP2) that is shown to promote the cell growth and proliferation of glioblastoma, yet the role of this gene in PD is unknown." (PMID 29163029, 2017). "miR-331-3p inhibits tumor growth, improves prognosis, and regulates the expression of NRP2, deoxyhypusine hydroxylase and the long non-coding RNA Hox transcript antisense intergenic RNA (HOTAIR) and human epithelial growth factor receptor 2 (HER2) in glioblastoma, prostate, and gastric cancers." (PMID 27548144, 2016). "EGFR, Integrin αvβ3, Neuropilin-2, and PDGFRα, but not CD90 and CD147, were significantly upregulated in glioblastoma than normal brain tissues by GEPIA analysis." (PMID 37146061, 2023).
gastric cancer (11 papers, 2011 to 2025). A primary or metastatic malignant neoplasm involving the stomach. "In TIM, cancer-associated fibroblasts (CAFs) promoted gastric cancer chemoresistance through NRP2 expression; NRP2 in macrophages promoted tumour growth by regulating the cytostatic effects of apoptotic tumour cells and coordinating immunosuppression." (PMID 36172369, 2022). "Analyzed by Kaplan–Meier survival curves, low expression levels of NRP2 in CAFs were associated with better overall survival (OS) of gastric cancer patients." (PMID 34826008, 2022). "Furthermore, IHC assay of gastric cancer specimens illustrated that low expression levels of NRP2 in CAFs were associated with better overall survival of gastric cancer patients." (PMID 34826008, 2022). "The activation of these pathways subsequently promotes cellular proliferation, survival, and invasive capabilities of cancer cells, underscoring the pivotal role of NRP-2 in gastric cancer pathology." (PMID 40430075, 2025). "Currently, research is being conducted to clarify the mechanisms of action of NRP-2 and to develop targeted therapeutic strategies with the potential to treat variety of malignancies, including gastric cancer." (PMID 40430075, 2025). "Tagln1 is usually upregulated in gastric cancer cells and activates the NRP2/VEGFR2 downstream MAPK signaling pathway, ultimately promoting angiogenesis." (PMID 39726754, 2024). "For example, CAFs expressing neuropilin 2 (NRP2) can reduce the sensitivity of gastric cancer cells to 5-fluorouracil (5-FU)." (PMID 37666813, 2023). "The results of the present study found that the VEGF/NRP2 signaling in CAFs can promote chemoresistance in gastric cancer." (PMID 34826008, 2022). "Together, these findings illustrated that NRP2 probably affect 5-FU sensitivity by downstream effector SDF-1 in gastric cancer." (PMID 34826008, 2022). "And the high expression of NRP2 was correlated with worse oncological outcomes in gastric cancer patients." (PMID 34826008, 2022). "Our results revealed that CAFs within gastric cancers promote chemoresistance through the expression of NRP2." (PMID 34826008, 2022). "Clinicopathological characteristics were further assessed by Cox proportional hazard ratio model, and we found that higher expression of NRP2 in CAFs was an independent prognostic factor in gastric cancer patients." (PMID 34826008, 2022). "Further the knockdown of the NRP2 significantly downregulated the 5-fluorouracil resistance in gastric cancer cells." (PMID 36550571, 2022). "For this purpose, we cultivated gastric cancer cells with CM collected from NRP2-sh CAFs and NRP2-nc CAFs, respectively." (PMID 34826008, 2022). "The present study indicated that CAFs within gastric cancers promote chemoresistance through the expression of NRP2." (PMID 34826008, 2022). "Inhibition of cell growth in cervical and gastric cancers by miR-331-3p was also reported via targeting NRP2 and E2F1 respectively." (PMID 34547721, 2021). "Serum sample 31# was from a gastric cancer patient, and the concentrations of Nrp1 and Nrp2 in the serum were 8630 and 8009 pg/mL, which were 12.9‐ and 17.4‐fold the mean values for serum from normal human samples." (PMID 30758083, 2019). "We first assessed the expression of NRP-2 protein in paraffin-embedded tissues of human gastric cancer and adjacent normal mucosa by immunoperoxidase staining." (PMID 22028766, 2011). "Based on the ligand-independent nature of NRP2 signalling observed in our study, a therapeutic approach to inhibit NRP2 biological activity in gastric cancer would be using RNA interference." (PMID 22028766, 2011). "In representative gastric cancer specimens, NRP-2 protein was expressed in the gastric cancer epithelium, but not in normal mucosal epithelium." (PMID 22028766, 2011). "We found that NRP-2 was overexpressed in human gastric cancer specimens and in gastric and carcinoid cells in vitro." (PMID 22028766, 2011).
gastric cancer (continued). "We utilized a shRNA-mediated RNA interference approach to suppress NRP-2 expression in gastric cancer cells to investigate the resulting phenotypic changes, including proliferative, migratory, and invasive activities." (PMID 22028766, 2011). "We observed that downregulation of NRP-2 in gastric cancer cells chemosensitized the cells to 5FU treatment." (PMID 22028766, 2011). "We demonstrate in this study that NRP-2 is highly expressed by tumor cells in gastric carcinoma tissues and by gastrointestinal cancer cell lines, but it is not detectable by immunohistochemistry in normal gastric mucosa." (PMID 22028766, 2011). "Neuropilin 2 (NRP-2) has emerged as an important factor in the progression of gastric cancer." (PMID 40430075, 2025). "Furthermore, we checked the expression of NRP2 in 72 gastric cancer specimens by immunohistochemistry (IHC) assay." (PMID 34826008, 2022). "CAFs promoted chemoresistance through Neuropilin 2 (NRP2) in gastric cancer." (PMID 36550571, 2022). "Then, NRP2 was knocked down with short hairpin RNA (shRNA) by lentivirus infection to investigate whether NRP2 contributes to 5-FU resistance in gastric cancer." (PMID 34826008, 2022). "Further studies are needed to determine whether NRP-2 mediates prosurvival functions in gastric cancer cells via S100A4." (PMID 22028766, 2011). "Therefore, we hypothesized that NRP2 promotes 5-FU resistance through the activation of YAP/TAZ in gastric cancer cells." (PMID 34826008, 2022). "Interestingly, Tsukamoto and colleagues found that 40% of gastric cancer patients analyzed had a gain at 2q33 (the region in which the NRP-2 gene is located) by array comparative genomic hybridization (CGH) analysis, suggesting copy number aberration (CNA) of this region." (PMID 22028766, 2011). "For further validation in a second gastric cancer cell line, NRP-2 was knocked down in NCI-N87 cells, which express a high endogenous level of NRP-2, by lentivirus-mediated stable shNRP-2 incorporation." (PMID 22028766, 2011). "One potential limitation of our study is that we analyzed the growth of NRP-2 knockdown gastric cancer cells as primary tumors but did not evaluate the metastasis of tumors." (PMID 22028766, 2011). "In human gastric cancer specimens, NRP-2 expression was detected in tumor tissues but not in adjacent normal mucosa." (PMID 22028766, 2011).
autism (10 papers, 2015 to 2025). Persistent deficits in social interaction and communication and interaction as well as a markedly restricted repertoire of activity and interest as well as repetitive patterns of behavior. "Here, we have demonstrated that mice with deficiencies in the autism candidate gene Nrp2 have deficits in reversal-learning strategies leading to impaired cognitive flexibility." (PMID 34663783, 2021). "Although the association between Nrp2 and human epilepsy is unclear, Nrp2 polymorphism is associated with autism in two patient populations." (PMID 34663783, 2021). "Pathogenic copy number variants as well as individual gene variants including the Sema 3F and NRP2 gene are associated with autism, epilepsy, intellectual disability, developmental delay, and dysmorphia in humans (NCBI-based ClinVar database 2017)." (PMID 30635860, 2019). "In contrast, Nrp2, a neuropilin family gene that controls neuronal migration and axon guidance, and has been associated with autism, wasup-regulated in female pups from dams having higher gestational FA." (PMID 25629700, 2015). "Nrp2-deficient mice show autism-like behavioral deficits and propensity to develop seizures." (PMID 34663783, 2021). "Positional and functional evidence has been indicated that polymorphisms and mutations in NRP2 may be associated with autism." (PMID 31354784, 2019). "Together, the coordinated downregulation of Nrp1, Nrp2, Robo2, and Dpysl3 suggests potential impairment in axon-guidance signaling cascades in autism." (PMID 41150532, 2025). "We recently characterized an ASD-linked gene deletion linked to vascular signaling, the neuropilin-2 knockout (NRP2) mouse, as a novel animal model of autism and epilepsy." (PMID 35883654, 2022). "Taken together, our results indicate that reduced Nrp2 signaling impacts the development of interneurons circuits contributing to autism-epilepsy comorbidity." (PMID 34663783, 2021). "Further studies of mouse KO models of ASD genes such as Sema 3F or NRP2 may be informative to clinical phenotypes contributing to the pathogenesis in autism and epilepsy patients." (PMID 30635860, 2019). "Thus, cellular localization and downstream signaling of neurovascular components may play a significant role in the phenotypes inducing autism-like behavior seen in NRP2 and Sema 3F KO mutants." (PMID 35883654, 2022). "Notably, Nrp2 is a strong candidate ASD gene on SFARI ranking system (Score 2) with two reported de-novo polymorphisms in Nrp2 gene in patients meeting diagnostic criteria for ASD using DSM-IV/DSM-V, Childhood Autism Rating Scale, and Autism Behavior Checklist." (PMID 39578518, 2025).
bladder cancer (10 papers, 2011 to 2023). "Overexpression of neuropilin-2 demonstrated to have prognostic value in bladder cancer, as it was associated with shorter overall and cancer-specific survival and earlier cancer-specific death after transurethral resection and radiochemotherapy." (PMID 29207682, 2017). "NRP2 was shown to be also a biomarker of potential clinical significance associated with bladder cancer progression." (PMID 24212788, 2011). "Because NRP2 expression is significantly associated with poor prognosis in renal cell carcinomas, colorectal carcinomas, gastric carcinomas, osteosarcoma, breast, pancreatic, and bladder cancer, it has become an attractive target for cancer therapy." (PMID 32038994, 2019). "Recent findings established the link between SPP1 and the epithelial-to-mesenchymal transition (EMT) through the NRP2 protein pathway in bladder cancer cell lines." (PMID 38067407, 2023). "In our previous study, the transmembrane protein neuropilin-2 (NRP2) emerged as a predictive marker in patients with bladder cancer." (PMID 33918816, 2021). "The human protein atlas (HPA) provides some information on the protein expression of NRP2 in bladder cancer tissue." (PMID 33918816, 2021). "In bladder cancer cell lines, TGFβ1 treatment significantly elevated NRP2 mRNA by five-fold while only a minor increase of the NRP2 protein level was observed in our hands." (PMID 33918816, 2021). "The aim of this study was to investigate the clinical relevance of NRP2 and its transcript variants in MIBC using data from the “The Cancer Genome Atlas” (TCGA) bladder cancer (BLCA) cohort." (PMID 33918816, 2021). "The NRP2 gene is reported as a prognostic indicator for reduced survival in bladder cancer patients." (PMID 32695477, 2020). "Neuropilin-2 (NRP2) is a prognostic indicator for reduced survival in bladder cancer (BCa) patients." (PMID 32038994, 2019). "Investigating the relevance of NRP2 transcripts as prognostic markers, NRP2A emerged as an independent prognostic marker for a shorter CSS in bladder cancer patients." (PMID 33918816, 2021). "Future research is needed to evaluate the exact mechanism of how NRP2 and GLI2 communicate bidirectionally, how NRP2 modulates SPP1 transcription, and what implications this will have for development and progression of other cancer entities apart from bladder carcinoma." (PMID 32038994, 2019). "Additionally, the co-expression of neuropilin-2 and the family member VEGF-C is also a prognostic marker for overall survival of bladder cancer patients." (PMID 29207682, 2017).
neuroblastoma (10 papers, 2010 to 2025). Neuroblastoma (NB) is the most common solid, extracranial childhood tumor. "Interestingly, a recent study linked upregulation of NRP2 with cisplatin-resistance in neuroblastoma cells." (PMID 34239847, 2021). "A study using tumor biopsies from children with neuroblastomas (NBs) to assess the mRNA expression of neuropilin with quantitative RT-PCR showed that NRP1 and NRP2 mRNA and protein levels are higher in stages I-IV NB compared to non-tumor controls." (PMID 37894289, 2023). "To test whether NRP2 is needed for RABV infection, we knocked down NRP2 expression by transfecting HEK293 cells and N2a cells (a mouse neuroblastoma cell line) with specific siRNA to NRP2 mRNA (siNRP2)." (PMID 40558096, 2025).